MIR544A (microRNA 544a)
Synonyms: hsa-mir-544; MIR544; MIRN544; hsa-mir-544a
Gene: MicroRNA gene on chromosome 14 (101,048,658 to 101,048,748, forward strand). Ensembl gene ENSG00000207587.
Gene Ontology:
Biological process: miRNA-mediated post-transcriptional gene silencing
Cellular component: RISC complex
Homologues: Orthologues: chimpanzee ptr-mir-544 (100% identical), macaque mml-mir-544 (100% identical), pig MIR544A (93% identical), dog MIR544 (92% identical), rat Mir544 (78% identical), mouse Gm54710 (43% identical).
Diseases named in the same sentence as MIR544A in open-access papers:
MIR544A is named in the same sentence as 3 diseases in open-access papers, as found by Europe PMC text mining. Sharing a sentence is not in itself a finding about the gene and the disease. The quoted sentences say what the papers report.
melanoma (1 paper, 2018). A malignant, usually aggressive tumor composed of atypical, neoplastic melanocytes. "This list included several oncogenes, namely MIR544A, MIR146B, FAM83A (also known as tumor antigen BJ‐TSA‐9), the cancer‐germline genes PBK (PDZ binding kinase) and PRAME (preferentially expressed antigen in melanoma), and GCKR that, with PRAME, is a downstream target of the BCR‐ABL protein." (PMID 29575763, 2018).
MIR544A also shares sentences with these, for which no sentence is quoted: breast cancer (1 paper); cancer (1).